HIF1A (hypoxia inducible factor 1 subunit alpha)
Diseases named in the same sentence as HIF1A in open-access papers (continued):
Sharing a sentence is not in itself a finding about the gene and the disease.
melanoma (continued). "In a murine melanoma model, inhibition of HIF-1α transcriptional activity results in CCL2- and CCL5-mediated increases in NK cells and CTLs in the tumor bed, and improves the antitumor potential of peptide vaccination and anti–PD-1 blocking antibody." (PMID 35499071, 2022). "In other words, the presence of HIF-1α in advanced melanoma suggests that melanoma is less dependent on oxidative phosphorylation and more on glycolysis for ATP production during hypoxia." (PMID 36620597, 2022). "Nevertheless, from a functional perspective, this work shows that in the presence of light microalgae were able to inhibit HIF-1α, therefore fulfilling the metabolic oxygen requirements of hypoxic melanoma cells." (PMID 36362338, 2022). "Using a recently published single-cell RNAseq dataset, we furthermore show that this positive correlation occurs either in melanoma subpopulations with a high HIF1α expression, or in tumors that with a high PD-L1 expression." (PMID 34268602, 2022). "Increased c-Myc and HIF-1α expression levels were also evident after IFN-γ treatment, which are associated with tumor metastasis and poor prognosis in melanoma patients." (PMID 35105915, 2022). "We evaluated the expression of HIF-1α, a surrogate marker of hypoxia, to estimate hypoxic conditions in several surgically resected oral melanoma tissues." (PMID 36669005, 2022). "We further explored the correlation between PD-L1 and HIF1α expression in subpopulations of melanoma cells, using the recently published single-cell RNA-sequencing (RNAseq) data of 33 melanoma tissues." (PMID 34268602, 2022). "Treatment of melanoma-bearing mice with acriflavine, reported to prevent HIF-1α/HIF-1β heterodimerization, improved immunotherapy strategies based on TRP-2 peptide vaccination and anti-PD-1 antibody." (PMID 35795658, 2022). "HIF-1a was 1.55-fold higher in the melanoma group compared with the control group (p < 0.05), while HIF-2a was 2.32-fold higher in the melanoma patients compared with the control patients (p < 0.05)." (PMID 36294785, 2022). "In some tumor types, such as melanoma, glioblastoma and colon cancer, HIF-1α expression has been found to be increased by adenosine-induced Atk and/or MAPK signal pathway activation." (PMID 34750517, 2022). "The lncRNA LINC00518 directly regulates levels of the hypoxia-inducible factor HIF1α and glucose consumption in melanoma cells and promotes melanoma invasion, tumor growth, and radio-resistance in mice xenografts." (PMID 35159386, 2022). "The relative expression level of the hub genes was reverified in melanoma cell lines, and showed that HIF1A, IL1B, HMOX1, MMP3, CDKN2A and TIMP1 were upregulated, while PTEN, PRKCA, ATF3 and BRAF were downregulated in melanoma samples." (PMID 36226170, 2022). "Our results highlight the relevance of Ezrin, L1CAM and HIF-1α as prognostic markers in melanoma patients." (PMID 36142656, 2022). "Hypoxia, as a major feature of solid tumors, activates HIF-1α that enhances tumor growth and leads to melanoma progression by regulating the expression of genes involved in angiogenesis, metabolism, cell proliferation, and metastasis." (PMID 35874683, 2022). "In the invasive MITF-low state PGC1α depletion rewires melanoma cells towards metabolic dependency on HIF1α-mediated glycolysis and glutamine usage." (PMID 35912100, 2022). "A similar effect has also been observed in melanoma cell lines, where adenosine stimulated A3AR causing HIF-1α over-expression in response to hypoxia." (PMID 34750517, 2022). "Next, we transduced several melanoma cell lines with the HIF1α targeting vector A9 or a control hsRNA and stimulated the cells for 24 h with 100 μM DFO or 1% O2 hypoxia." (PMID 34268602, 2022). "In this paper, BNIP3-melanoma cells display increased intracellular Fe(II) levels, caused by an elevated, NCOA4-mediated ferritinophagy, the latter fostering PHD2-mediated HIF-1α destabilization." (PMID 35682788, 2022).
melanoma (continued). "Meanwhile, the HIF1a/HIF2a ratio was 1.5-fold lower in the melanoma group compared with the control group (p < 0.05)." (PMID 36294785, 2022). "Glucose restriction also activates theAKT pathway in melanoma cells, which contributes to the activationof HIF-1α." (PMID 36018000, 2022). "The HIF-1α target gene GLUT1, was found to be elevated in metastatic and BRAFV600E mutated melanoma cell lines under hypoxic conditions." (PMID 33964953, 2021). "Microarray experiments have shown that melanoma cell lines with BRAFV600E displayed increased HIF1A expression." (PMID 34831420, 2021). "Hypoxia-related HIF-1α stabilization has been also reported to enhance expression/activation of the Met proto-oncogene in melanoma cells, which in turn promotes formation of capillary-like structures by vasculogenic mimicry." (PMID 33964953, 2021). "An elevated HIF-1α level was associated with increased expression and activation of RhoA, as well as higher migratory potential of HT168-M1 melanoma cell line." (PMID 33918883, 2021). "Another study found that HIF1A contributes to melanoma invasion and metastasis via the activation of SRC, an oncogene, while the inactivation of HIF1A reduced metastasis." (PMID 34831420, 2021). "Radioresistant melanoma cell line was resensitized following treatment with HIF-1α inhibitor—2-methoxyestradiol." (PMID 33918883, 2021). "Performing chromosome immunoprecipitation and luciferase reporter assays, the direct binding of HIF-1α to HRE element in the PD-L1 proximal promoter was demonstrated in melanoma cells." (PMID 33964953, 2021). "Low levels of oxygen reduce MITF expression in melanoma in an indirect hypoxia-inducible factor 1 subunit alpha (HIF-1α)-dependent manner, thereby promoting the invasive, metastatic phenotype." (PMID 34071193, 2021). "Melanoma cells have been shown to express hypoxia-inducible factor 1 alpha (HIF1α) at an abnormally high level under normoxia, which shifts the central carbon metabolism in favor of aerobic glycolysis." (PMID 34822435, 2021). "We investigated the impact of inhibiting HIF-1α transcriptional activity on cytotoxic immune cell infiltration into B16-F10 melanoma." (PMID 34155342, 2021). "As expected, combining the HIF-1α inhibitor echinomycin with chloroquine improved melanoma cytotoxicity under hypoxic conditions." (PMID 34360634, 2021). "MiR-33a-3p was decreased in WM451 and A375 cells, which have a high invasive and metastatic tendency, while HIF-1α was increased in melanoma WM451 and A375 cells." (PMID 33664256, 2021). "On the other hand, MITF expression in primary melanocytes and melanoma cells is suppressed under hypoxic conditions by the HIF-1α mediated activation of a transcriptional repressor, the differentially expressed in chondrocytes protein-1." (PMID 33964953, 2021). "Mechanistically, U34 enzymes promote glycolysis through direct translational regulation of HIF1α mRNA that consequently maintains high levels of HIF1α protein to facilitate reactivated glycolytic networks in MAPKi resistant melanoma cells." (PMID 34830962, 2021). "Hypoxic stress reportedly increases the expression of Cx43 by transcriptional activation through HIF‐1α in melanoma cells in cancer." (PMID 34698450, 2021). "On the other hand, miR-199a-5p, miR-18b, miR-138 and miR-33a/b have been reported to inhibit proliferation, tumor growth, and invasion in melanoma by targeting HIF-1α." (PMID 33964953, 2021). "Several studies have demonstrated that HIF-1α can be regulated by miR-210 and miR-138 in melanoma cells." (PMID 33919449, 2021). "For example, HIF1A mRNA is stabilized by m6A deposition, while in melanoma cells high levels of HIF1α protein are maintained by modifications at the U34 wobble position of tRNAs." (PMID 33461542, 2021).
melanoma (continued). "We evaluated the expression pattern of hypoxia inducible factor 1 subunit alpha (HIF1A) in four different melanoma cell lines." (PMID 33946525, 2021). "This lncRNA is overexpressed in melanoma and triggers radioresistance by regulating glycolysis through miR-33a-3p/HIF-1α axis." (PMID 34638331, 2021). "This indicates the importance of a HIF1A-induced glycolytic metabolism in melanoma progression and metastasis, and a possible correlation between a glycolytic metabolism and tumor invasion and metastasis." (PMID 34831420, 2021). "Multiple signaling pathways have already been activated from the primary melanoma stage, whereas HIF1α, the major hypoxia-inducible factor, can be exclusively observed in metastatic melanoma cells." (PMID 33922182, 2021). "Overall, SOX2 plays a key role in inhibiting HIF1A and inducing oxidative phosphorylation and enabling melanoma cells to shift metabolism in response to an acidic microenvironment." (PMID 34831420, 2021). "A broad spectrum of molecules of natural origin with direct in vitro and in vivo pharmacological effects on migration and/or metastasis of melanoma cells have been evaluated, among which also molecules affecting HIF-1α expression." (PMID 33964953, 2021). "Of note, melanogenesis can stimulate HIF1α expression and anaerobic glycolysis in melanoma cells explaining in part the correlation between defects in VDR expression and signaling and defective responses to vitamin D in pigmented melanoma cells." (PMID 34692525, 2021). "These varied growth conditions induce several stress adaptive pathways in melanoma cells, such as the HIF1α pathway, p38 MAPK pathway, and integrative stress response (ISR), which are generally believed to be essential drivers of phenotype switching." (PMID 34604096, 2021). "A transferrin-polyethylenimine-HIF-1α–short-hairpin RNA complex was used to target HIF-1α obtaining a dramatic inhibition of tumor growth in melanoma xenograft model." (PMID 33964953, 2021). "This is consistent with recent reports that show BRAFi treatment induces degradation of HIF-1α at both mRNA and protein levels in drug-tolerant BRAF-mutated melanoma cells." (PMID 32923395, 2020). "We and others have previously shown that HIF1α expression is significantly higher in MM than primary melanomas and nevi." (PMID 33552976, 2020). "HIF1α a major angiogenesis inducer in tumor cells (carcinoma and melanoma) both in vitro and in vivo." (PMID 32211322, 2020). "The HIF-1α/VEGF signaling pathway has been demonstrated to play a role in the progression of melanoma metastasis." (PMID 32596377, 2020). "The small molecule methyl sulfone, has been shown to normalize the pro-metastatic metabolism of hypoxic melanoma cells via downregulating the expression of HIF-1α and, amongst others, simultaneously also reducing miR-210 expression." (PMID 31906510, 2020). "LCN2 expression was also reported to be increased in tumor cells cultured under hypoxic conditions and paralleled the levels of HIF-1A in mouse melanoma cells." (PMID 33604288, 2020). "This study demonstrates a decrease in HIF1α protein levels only in melanoma cells treated with NTP+TPZ and expressing high gap junctions (NTP+TPZ “C”)." (PMID 32973969, 2020). "HIF-1α not only regulates both anaerobic and aerobic glycolysis in melanoma cells, but also enhances the expression of genes involved in both tumor invasion and glycolysis." (PMID 32528879, 2020). "For example, exosomes derived from melanoma are capable of inducing expression of pro-angiogenic and inflammatory genes including hypoxia-inducible factor 1 alpha (HIF-1α) and TNF-α in lymph nodes." (PMID 33291683, 2020). "In melanoma, syntenin induces angiogenesis by activating Akt, leading to the expression of HIF-1α and the transcription of IGF-binding protein-2 (IGFBP-2), which induces the production of VEGF in endothelial cells and angiogenesis." (PMID 32106836, 2020).
melanoma (continued). "First, in a model of melanoma it was demonstrated that the PKA scaffold protein AKAP12v2 is a direct transcriptional target of HIF-1α, and its hypoxic induction effectively enhances the migratory capacity of melanoma cells." (PMID 32111982, 2020). "To address the effect of ACF on the expression levels of PDK1 and VEGF in melanoma cells, we then conducted knock-down experiments of HIF-1α." (PMID 33396270, 2020). "The supplementation of ascorbic acid in melanoma cell lines contributes to the regulation of HIF1-α activity and accumulation." (PMID 33352824, 2020). "A prominent example of a miRNA regulated by specific transcription factors is miR-210, which is regulated by binding of HIF1α by a specific response element in the miRNA-precursor sequence in melanoma and also in HCC." (PMID 31906510, 2020). "Erk and Akt are two key downstream effectors of MAPK and PI3K signaling pathways, respectively, both of which can control HIF-1α/VEGF axis in melanoma." (PMID 33424993, 2020). "The mechanisms that allow melanocytes and melanoma cells to survive under this oxidative stress are unclear, however, some evidence points to the involvement of HIF-1α." (PMID 33396270, 2020). "Since the activity of ACF on melanoma cells has not been assayed in detail to date, here we examined the effect of this drug on the metabolism and progression of melanoma under normoxic expression of HIF-1α." (PMID 33396270, 2020). "Here, we used acriflavine, a chemical inhibitor of HIF-1α, to investigate the role of this transcription factor on the progression of melanoma under normoxic conditions." (PMID 33396270, 2020). "Here, we analyzed the effect of ACF, a HIF-1α inhibitor, on melanoma cells maintained at 5 mM glucose." (PMID 33396270, 2020). "H1 receptor antagonists significantly improved overall survival rates and suppressed tumor growth through the inhibition of hypoxia inducible factor-1 alpha (HIF-1α) expression in B16F10 melanoma-bearing mice." (PMID 30678047, 2019). "In our study, HIF-1α was expressed in BRAFV600E melanoma cells in hypoxia and to a lesser extent in normoxia, whereas in HRASQ61R melanoma cells oxygen concentration had to be reduced to 1% to stimulate HIF-1α expression." (PMID 31461993, 2019). "Our study demonstrates the role and clinical relevance of miRNA-138 and HIF1α in melanoma cell growth and metastasis, providing a novel therapeutic target for suppression of melanoma growth and metastasis." (PMID 31371307, 2019). "Consistently, the protein level of PDK1 was increased in melanoma cells with Ku80 overexpression, which was reverted in part by knockdown of HIF1-α." (PMID 31023624, 2019). "Analyzing murine B16 melanoma tumor tissues, we found a positive correlation between hypoxia, measured by HIF-1α accumulation, and EGFR levels." (PMID 31717697, 2019). "In melanoma, the downstream signal regulation mechanism of HIF1α is still under further study by ourselves." (PMID 31371307, 2019). "Their observations in B16 melanoma cells and in tumour xenografts seem to indicate that miR-199a-5p is a tumour suppressor, via direct targeting of HIF-1α." (PMID 30651148, 2019). "Here we found that the MNK1/2 inhibitor cercosporamide diminished CoCl2-induced HIF-1α accumulation in melanoma cells, indicating that eIF4E phosphorylation is required for CXCR7-facilitated translation of HIF-1α." (PMID 30804329, 2019). "MITF activity is tightly regulated in melanocytes and melanoma, including transcriptional repression by HIF-1α." (PMID 31461993, 2019). "Hypoxia exposure of DU145 and MDA-MB-231 cells led to the upregulation of PD-L1 expression in a HIF-1α dependent manner, where HIF-1α suppression led to a reduction in PD-L1 mRNA and cell surface protein in human prostate and murine melanoma cells." (PMID 31835751, 2019).
melanoma (continued). "To summarize, we identified miRNA-138 as a regulator for controlling melanoma cell proliferation, invasion and metastasis, and revealed a novel mechanism by which miRNA-138 negatively regulates the HIF1α to suppress melanoma growth and metastasis." (PMID 31371307, 2019). "Melanogenesis induction in melanoma cells upregulates HIF-1α-related pathways, including stress response-related pathways, glucose metabolism and angiogenesis." (PMID 30718742, 2019). "Overexpression of miRNA-138 or inhibition of HIF1α significantly suppressed the growth and metastasis of melanoma in vivo." (PMID 31371307, 2019). "As anticipated, DMOG transiently induced HIF1α expression and increased invasiveness in both IGR37 and 501mel human BRAFV600E‐mutated melanoma cell lines." (PMID 31207090, 2019). "Here, we found that miRNA-138 was lowly expressed and hypoxia-inducible factor 1α (HIF1α) was highly expressed in patients’ melanoma tissue compared with the paracancerous tissues, and they had a significant negative correlation (r=−0.877, P<0.001)." (PMID 31371307, 2019). "Further studies showed that exogenous overexpression of miRNA-138 or knockdown HIF1α inhibits melanoma cell growth and metastasis, both in vitro and in vivo." (PMID 31371307, 2019). "We further examined the difference of the miRNA-138 and HIF1α expression at different stages of melanoma." (PMID 31371307, 2019). "The results showed that siRNA HIF1α (si-HIF1α) inhibited melanoma proliferation, migration and invasion in WM35 cells." (PMID 31371307, 2019). "In conclusion, with this study we would propose a thigh correlation between SOX2 expression and OxPhos metabolism in melanoma cells, under a condition of reduced HIF1α expression." (PMID 30466459, 2018). "The aim of our work was to combine the action of an anti-vascular drug - DMXAA with HIF-1α inhibitor - digoxin in the treatment of mice with B16-F10 melanoma tumors and to examine the mechanism of action of this combination." (PMID 29743548, 2018). "The proliferation of BrafV600E; Phd2−/− melanoma cells was also significantly slowed down after silencing HIF-1α or HIF-2α." (PMID 30575721, 2018). "Administration of DMXAA to mice bearing B16-F10 melanoma increases the amount of HIF-1α transcription factor in tumors comparing to the control mice that received the PBS− solution." (PMID 29743548, 2018). "Our analysis of TCGA SKCM data discovers a novel PHD2-P317S mutation in melanoma and this mutation also resulted in deficiency of PHD2 interaction with HIF-1α in human melanocytes." (PMID 30575721, 2018). "Consistently, overexpression of SOX2 in 501-Mel melanoma cells drastically reduced HIF1α mRNA and protein expression." (PMID 30466459, 2018). "It depolymerizes microtubules and prevents HIF1α nuclear accumulation, increasing the radiosensitivity of NPC stem cells and melanoma cells by inactivating NF-κB/HIF1 or HIF1α/PDK1 signaling pathway." (PMID 29688867, 2018). "This is likely true mainly in conditions when SOX2 exceeds HIF1α in terms of protein expression, as in the case of acidosis-exposed melanoma cells." (PMID 30466459, 2018). "More importantly, α-MSH-induced LC3-ΙΙ and cleaved caspase-3 were partially abrogated in B16-F10 melanoma cells transfected with HIF-1α shRNA during hypoxia." (PMID 30062060, 2018). "Comparisons between the groups with high and low expression of hypoxia inducible factor (HIF)-1α regarding their general characteristics and aggressiveness markers of melanoma." (PMID 29755400, 2018). "Here we show for the first time that SOX2 is highly expressed in melanoma cells exposed to extracellular acidosis, where it modulates cell metabolism in order to favor an oxidative phenotype, possibly interfering with HIF1α expression." (PMID 30466459, 2018). "We also treated the BrafV600E; Phd2−/− melanoma cells under 1% oxygen and demonstrated that hypoxia further stabilized HIF-1α and HIF-2α expression with increased pAkt and pS6K levels." (PMID 30575721, 2018).